SAE1 (SUMO1 activating enzyme subunit 1)
Description:
The heterodimer acts as an E1 ligase for SUMO1, SUMO2, SUMO3, and probably SUMO4. It mediates ATP-dependent activation of SUMO proteins followed by formation of a thioester bond between a SUMO protein and a conserved active site cysteine residue on UBA2/SAE2.
Synonyms: AOS1; SUA1; UBLE1A; FLJ3091; HSPC140
Tractability: Small molecule: a structure with a bound ligand is known; a high-quality ligand is known; it has a high-quality binding pocket; it belongs to a druggable protein family. PROTAC: ubiquitination databases record sites on it; its protein half-life has been measured; a small molecule that binds it is known.
Chemical probes: Subasumstat (high quality)
Gene: Protein-coding gene on chromosome 19 (47,113,274 to 47,210,636, forward strand). Ensembl gene ENSG00000142230.
Subcellular location: Nucleus
Subcellular location (Human Protein Atlas): Cytosol; Nucleoplasm
Pathways (Reactome):
Metabolism of proteins: SUMO is conjugated to E1 (UBA2:SAE1); SUMO is transferred from E1 to E2 (UBE2I, UBC9)
Gene Ontology:
Molecular function: ATP-dependent protein binding; protein binding; protein heterodimerization activity; small protein activating enzyme binding; SUMO activating enzyme activity; enzyme activator activity; ubiquitin activating enzyme activity; ubiquitin-like modifier activating enzyme activity
Biological process: positive regulation of establishment of protein localization to mitochondrion; positive regulation of protein sumoylation; protein sumoylation; protein ubiquitination
Cellular component: cytosol; nucleoplasm; nucleus; SUMO activating enzyme complex
Genetic constraint (gnomAD): Loss-of-function variants: 7 observed, 26.81 expected, observed/expected ratio (o/e) 0.26, 90% interval 0.15 to 0.49. The upper end of that interval is the gene's LOEUF score, 0.49, which puts it in group 2 of 6, group 1 being the genes least tolerant of losing a copy. Missense variants: 326 observed, 404.42 expected, observed/expected ratio (o/e) 0.81, 90% interval 0.74 to 0.88. Synonymous variants: 149 observed, 149.4 expected, observed/expected ratio (o/e) 1, 90% interval 0.87 to 1.14.
Homologues: Orthologues: chimpanzee SAE1 (100% identical), guinea pig SAE1 (94% identical), mouse Sae1 (93% identical), rat Sae1 (92% identical), pig SAE1 (89% identical), dog SAE1 (88% identical), rabbit SAE1 (86% identical), macaque SAE1 (72% identical), tropical clawed frog sae1 (71% identical), zebrafish sae1 (69% identical), Drosophila melanogaster Aos1 (40% identical), Caenorhabditis elegans aos-1 (32% identical). Paralogues in human: UBA1 (31% identical), UBA6 (29% identical), UBA7 (29% identical), NAE1 (28% identical), ATG7 (12% identical), UBA2 (9% identical), UBA3 (9% identical), MOCS3 (8% identical), UBA5 (7% identical).
Diseases named in the same sentence as SAE1 in open-access papers:
SAE1 is named in the same sentence as 68 diseases in open-access papers, as found by Europe PMC text mining. Sharing a sentence is not in itself a finding about the gene and the disease. The quoted sentences say what the papers report.
myositis (21 papers, 2017 to 2026). "The precise roles of myositis-associated autoantibodies, such as anti-Ro52, require further elucidation, alongside lesser-studied antibodies like anti-SAE1." (PMID 39316320, 2024). "About myositis autoantibodies, the most frequent MSAa in IIMs were anti-SAE1 (12.5%), anti-MDA5 (10.7), and anti-TIF1g (10.7%)." (PMID 41993189, 2026). "A myositis panel resulted positive for anti-small ubiquitin-like modifier-1 activating enzyme (SAE1), so she was diagnosed with anti-SAE1 amyopathic DM." (PMID 40584538, 2025). "Myositis-specific (Mi2, TIF1g, MDA5, NXP2, SAE1, Jo1, SRP, PL7, PL12, EJ, OJ), myositis-associated (Ku, PM-Scl 75/100, Ro52), and antinuclear antibodies were negative." (PMID 35725460, 2022). "Regarding laboratory analyses, myositis-specific antibodies were detected with similar frequencies in patients with concomitant SjD (PM-Scl-100 + SAE1 + PM-Scl75, PM-Scl100, SRP, MDA5 + SRP, Mi-2alpha + Mi2ß, each n=1) and those without coexisting SjD (SRP (n=2), NXP2 (n=1))." (PMID 40995369, 2025). "Notably, anti-Jo-1 and Mi2 IgG were found to be absent in sera of 26 SjD patients and were only detected in patients with myositis, Similarly, anti- SAE1/SAE2 IgG is reported to be exclusively found in serum of patients with Myositis." (PMID 39936155, 2024). "Notably, one female patient aged between 70 and 75 years initially presented with ILD and was classified as having interstitial pneumonia with autoimmune feature (IPAF) with strong SAE1 autoantibody detection at disease onset but then developed myositis 1 year later and re-classified as PM." (PMID 39575249, 2024). "Myositis-specific (anti-Mi2, NXP2, SAE1, MDA5, TIF1γ, Jo1, PL7, PL12, EJ, OJ, KS, Zo, Ha, SRP) and myositis-associated (anti-Ro52, U1RNP, Ku, PmScl, cN1A) antibodies in addition to anti-HMGCR were rare, only occurring in nine (8.3%) patients." (PMID 40347460, 2025). "Among the seven patients who tested strongly positive for the anti-SAE1 autoantibody and met the criteria for IIM, three were diagnosed with DM, two with CADM, one with PM, and one with OM in the context of concurrent myositis and SSc." (PMID 39575249, 2024). "In the group of patients who tested strongly positive for anti-SAE1 autoantibodies, three were diagnosed with CTD other than myositis: one with MCTD, one with UCTD, and one with spondyloarthritis." (PMID 39575249, 2024). "On laboratory testing, serum creatine kinase (CK) activity is often elevated and, in addition, myositis specific antibodies (MDA-5, NXP-2, Mi-2, TIF1-γ, SAE-1) can be found in ~60% of patients." (PMID 35457124, 2022). "A parallel between the clinical course of myositis and cancer was observed in patients carrying anti-TIF1, anti-NXP2, anti-SAE1, anti-Jo-1, anti-PL-12, and anti-HMGCR antibodies, and in the MSAs- patients." (PMID 29178913, 2017). "In contrast, none of the remaining three patients who tested strongly positive for anti-SAE1 autoantibodies but were diagnosed with CTD without myositis displayed a concordant ANA IIF pattern." (PMID 39575249, 2024). "In a nationwide study on the prevalence of MSAs in the Netherlands (Euroline myositis line-blot assay; Euroimmun), out of 88 patients with an MSA, 49% of MSAs were DMSAs, with relative proportions ranging between 15% (anti-TIF1-γ) and 2% (anti-SAE-1)." (PMID 35457124, 2022). "Myositis antibodies to any of the following antigens were found in 45/224 (20%) patients included in the assay: PL-7, SSA/Ro52, Mi-2 alpha, Mi-2beta, PM-cl75, PM-Scl100, Jo-1, Ku, PM-Scl75, SRP, TIF1gamma, SAE1, SAE1/SUMO1, Mi2, PL12." (PMID 33735220, 2021). "In addition to patients with IIMs with autoantibodies to TIF1-γ, NXP2 and SAE1, we also noted that in some cases in the anti-ARS group (anti-Jo-1 and anti-PL-12) there was temporally proximate occurrence of the cancer and myositis onset." (PMID 29178913, 2017).
myositis (continued). "Few studies have reported the clinical utility of LIA in detecting anti-SAE1 autoantibody and its impact on different clinical subsets, including patients with IIM or other CTDs without myositis in Asian cohorts, considering the low prevalence of anti-SAE1 autoantibody among Asians." (PMID 39575249, 2024). "The autoimmune serum profile for specific myositis autoantibodies was investigated: ANA, anti-Mi2/alpha and beta nucleosome remodeling and deacetylase complex, anti-SRP, PL7, PL-1, EJ, OJ, Jo 1, PM-Scl100 and PM-Scl75, Ro-52, NXP2, TIF 1g, SAE1 and MDA5 resulted inconclusively." (PMID 37147490, 2023).
breast carcinoma (12 papers, 2015 to 2024). "SAE1 was highly expressed in breast cancer, and its overexpression was associated with poor prognosis of breast cancer patients." (PMID 39742381, 2024). "Single-cell analysis, using CancerSEA, was performed to query which functional states are associated with SAE1 in different cancers in breast cancer at the single-cell level." (PMID 34621746, 2021). "To better understand the relevance and underlying mechanisms of SAE1 expression in breast cancer, we investigated the functional state of SAE1 in single-cell level via the CancerSEA database." (PMID 34621746, 2021). "SAE2 is necessary for Myc-dependent tumor growth in mice, and a gene expression analysis of human breast cancer with high Myc showed that lower SAE1 and SAE2 abundance in tumors is associated with a longer survival period without metastasis." (PMID 33968766, 2021). "Our study showed that the proliferation and cell cycle progression of breast cancer cells were significantly inhibited after SAE1 inhibition in vitro." (PMID 39742381, 2024). "In total, 159 cases of breast cancer patients were divided into high and low expression groups based on SAE1 expression levels." (PMID 39742381, 2024). "We performed immunohistochemistry to analyze SAE1 expression in BC tissues and para-cancer tissues in 79 breast cancer patients." (PMID 39742381, 2024). "We used siRNA to knock down SAE1 expression in T47D and BT-549 cells, and the results showed that this knockdown significantly inhibited breast cancer cell proliferation and the cell cycle process." (PMID 39742381, 2024). "In this study, the Cancer Genome Atlas (TCGA), Gene Expression Omnibus (GEO), and Kaplan-Meier plotter databases were applied to analyze SAE1 expression in breast cancer and its relationship with patient prognosis." (PMID 39742381, 2024). "We also investigated the relationship between SAE1 and the clinicopathologic characteristics of breast cancer patients through clinical samples." (PMID 39742381, 2024). "The SAE1 protein expression varies among different breast cancer cell lines and normal mammary cell lines." (PMID 39742381, 2024). "The purpose of this study was to analyze SUMO activating enzyme subunit 1 (SAE1) expression in breast cancer (BC)." (PMID 39742381, 2024). "The results showed that SAE1 protein expression in breast cancer tissues was significantly higher than that in para-cancerous tissues." (PMID 39742381, 2024). "To investigate the biological function of SAE1 in breast cancer cells (T47D, BT-549), we knocked down the SAE1 expression level in cells by transfecting with siRNA." (PMID 39742381, 2024). "The results showed that the SAE1 mRNA expression level in breast cancer was significantly higher than that in normal tissue." (PMID 39742381, 2024). "In the present study, both bioinformatics analysis of the TCGA and GEO databases and immunohistochemical assay of clinical tissue samples showed that SAE1 was highly expressed in breast cancer." (PMID 39742381, 2024). "Knocking down SAE1 effectively inhibited breast cancer cell proliferation and its cell cycle process." (PMID 39742381, 2024). "We also verified the SAE1 protein level in 79 breast cancer tissues and 36 para-cancerous tissues by IHC." (PMID 39742381, 2024). "For example, several studies have shown that the expression level of SAE1 is increased in some cancer types, such as hepatocellular carcinoma, breast cancer, gastric cancer, pancreatic cancer, and lung cancer." (PMID 37705041, 2023). "Previous studies have shown that higher SAE1 and SAE2 expressions in patients with breast cancer are associated with significantly higher instances of metastasis and poor prognosis." (PMID 37886949, 2023). "Patients with breast cancer who have Myc overexpression and low expression of SAE1/2 show significantly reduced cancer cell metastasis and improved survival compared with those with high SAE1/2 expression." (PMID 37143582, 2023).
breast carcinoma (continued). "Next, we found that the average mRNA expression of SAE1 was higher in TNBC patients compared with luminal A or luminal B breast cancer subtypes based on GEO database GSE31448, GSE45827, and GSE65216." (PMID 34621746, 2021). "Breast cancer patients with lower SAE1 expression have been reported to have significantly lower instances of metastatic cancer and increased survival compared to those that express a higher level of SAE1." (PMID 32467670, 2020). "However, the possible mechanism of SAE1 affecting the biological function of breast cancer cells and the prognosis of patients with breast cancer has, to date, not been reported." (PMID 39742381, 2024). "To verify SAE1 expression in breast cancer tissues and normal breast tissues, we analyzed data of SAE1 mRNA expression in 1095 breast cancer tissues and 113 normal tissues from the TCGA database and in 104 breast cancer tissues and 17 normal tissues from the GEO dataset GSE42568." (PMID 39742381, 2024). "The biological function of SAE1 was also studied in breast cancer cells in vitro." (PMID 39742381, 2024). "Multivariate Cox regression analysis showed that SAE1 may be an independent prognostic factor for the OS of breast cancer patients." (PMID 39742381, 2024). "Finally, we can now better understand the role of SAE1 in the tumorigenesis and development of breast cancer and thus its possible value in breast cancer diagnosis, treatment, and prognosis evaluation." (PMID 39742381, 2024). "Multivariate Cox regression analysis showed that SAE1 may be an independent prognostic factor for the OS of breast cancer." (PMID 39742381, 2024). "The results indicate that SAE1 may affect the progression of breast cancer by regulating the cell cycle, DNA damage, DNA repair, and cell proliferation." (PMID 34621746, 2021). "Furthermore, SAE2 is required for Myc-dependent tumor growth in mice, and the analysis of gene expression in Myc-high human breast cancer suggests that low expression levels of SAE1 and SAE2 are correlated with longer metastasis-free survival of breast cancer patients." (PMID 33968766, 2021). "Subsequently, WB was performed to detect SAE1 expression in normal breast epithelial cell (MCF-10A) and some breast cancer cell lines." (PMID 39742381, 2024). "For instance, high SAE1 and UBA2 (SAE2) levels are correlated with decreased survival and increased metastatic ability in patients with breast cancer." (PMID 32938830, 2020). "Moreover, SAE1 overexpression significantly correlated with poor OS, RFS, and DMFS of breast cancer patients." (PMID 39742381, 2024). "The biological function of SAE1 may be achieved through the PI3K/Akt/mTOR signaling pathway, and SAE1 is a potential target for breast cancer treatment." (PMID 39742381, 2024). "The SUMO-activating enzyme subunit 1⁄2 (SAE1/SAE2) may promote metastasis in MYC-driven breast cancer, and the SUMO-conjugating E2 enzyme UBC9 has also been shown to advance metastasis in breast cancer." (PMID 35408841, 2022). "Breast cancer patients with lower SAE1 and SAE2 expression have significantly lower instances of metastatic cancer and increased survival compared to patients with higher SAE1 and SAE2 levels." (PMID 31345225, 2019). "Moreover, the SUMO E1 enzyme (SAE1/2), was identified as synthetic lethal with c-myc in a genome-wide RNAi screen, and SAE2 is required for growth of Myc-dependent breast cancer in mice." (PMID 25860128, 2015). "The MYC oncogene is a frequently amplified in human cancer and a recent synthetic lethal shRNA screen identified SAE1 and SAE2 (the two heterodimer components of the SUMO E1) as top hits that confer synthetic lethality in breast cancer cells with high MYC activity." (PMID 25860128, 2015).
glioma (12 papers, 2019 to 2024). A benign or malignant brain and spinal cord tumor that arises from glial cells (astrocytes, oligodendrocytes, ependymal cells). "In this study, we have discovered SAE1 upregulation is directly associated with glioma tumor stage and patient survival." (PMID 31345225, 2019). "Next we analyzed associations of SAE1 expression, Akt SUMOylation and phosphorylation in glioma cells." (PMID 31345225, 2019). "We also paid attention to the association between SAE1 expression and the clinicopathologic features of human gliomas." (PMID 31345225, 2019). "The bioinformatics analysis of SAE1 from these two databases demonstrated that high expression of SAE1 is associated with poor survival and prognosis of patients suffering from glioma, liver cancer, renal cancer and thyroid cancer." (PMID 31345225, 2019). "A high-expression of SAE1 was significantly associated with the grade III-IV gliomas, whereas a low-expression of SAE1 was more often associated glioma with grade I-II (P = 0.032)." (PMID 31345225, 2019). "Furthermore, high protein expression of SAE1 is associated with poor prognosis of glioma patients." (PMID 34503213, 2021). "In lung adenocarcinoma and glioma, studies have shown that SAE1 expression upregulation promoted AKT sumoylation, further promoting AKT phosphorylation, thereby activating the AKT signaling pathway." (PMID 39742381, 2024). "It has been revealed that upregulated SAE1 is related with a higher grade of tumor malignancy and poor prognosis in glioma patients." (PMID 37886949, 2023). "Previous studies have shown that upregulated SAE1 promotes cell proliferation in hepatocellular carcinoma and promotes cell progression in vitro and in vivo in gliomas." (PMID 37886949, 2023). "SAE1 expression positively correlates with phosphorylation of Akt SUMOylation and Ser473 and controls the growth and malignancy of gliomas." (PMID 37786890, 2022). "It has been reported that SAE1 can mediate the progression of human glioma by activating the AKT signaling pathway through SUMOylation." (PMID 35606717, 2022). "Reported overexpression of SAE1 in glioma in a stage-dependent manner suggests it has a probable role in cancer initiation and progression." (PMID 33477333, 2021). "Reported overexpression of SAE1 in a stage-dependent manner in glioma by activating AKT SUMOylation-mediated signaling pathways suggested a probable role of SAE1 in cancer initiation and progression." (PMID 34621746, 2021). "Recently, the SUMO-activating enzyme SAE1 was found to promote human glioma progression by enhancing Akt SUMOylation-mediated signaling and propose targeting Akt SUMOylation as a promising therapeutic strategy." (PMID 34242346, 2021). "SAE1 has been found to play a significant role in various tumorigenesis and development, such as glioma, colon cancer, and non-small cell lung cancer." (PMID 34621746, 2021). "This is due to SAE1 upregulation promoting glioma cell growth and cell migration in vitro and in vivo through improving Akt SUMOlyation and Akt phosphorylation." (PMID 31345225, 2019). "We identified SAE1 upregulation in glioma through the differential proteome dissection between HGTs and PBTs, in which totally 70 differential proteins with at least 2-times’ changes." (PMID 31345225, 2019). "In particular, SAE1 was high expression in 69.6% (48/69) human glioma tissues, with an average staining score 7.76 ± 0.32 and other 21 cases (30.4%, 10/69) showed low SAE1 expression with mean staining scores 3.19 ± 0.22." (PMID 31345225, 2019). "Targeting SAE1 expression by small molecular inhibitors or RNAi is feasible way to discover novel drugs for glioma therapy." (PMID 31345225, 2019). "To further verify the tumor suppression effect of SAE1 knockdown in vivo, we compared if the mouse tumor, which was inoculated U87 cells to form glioma xenograft, was suppressed by SAE1 siRNA treatment." (PMID 31345225, 2019).